HBP1 (HMG-box transcription factor 1)
Diseases named in the same sentence as HBP1 in open-access papers (continued):
Sharing a sentence is not in itself a finding about the gene and the disease.
tumor (continued). "Patients with low tumor expression of GNG12, HBP1 and SESN1 genes presented reduced OS and worse RFS, compared to patients with high expression of these genes." (PMID 34681793, 2021). "IHC indicated that both HBP1 and Ki67 stained cells were reduced in the siHBP1-treated nude mice, which suggested that HBP1 knockdown decreased NPC tumor growth." (PMID 29367693, 2018). "Exosomal miR-29a-3p was then observed to migrate to the LNs and downregulate High-mobility group box transcription factor 1 (Hbp1) in Polymorphonuclear Myeloid-derived suppressor cells (PMN-MDSCs), inducing the formation of a microenvironment suitable for tumor colonization." (PMID 39191749, 2024). "Methylated HBP1 can decrease protein stability by promoting its ubiquitination and proteasome-mediated degradation, thereby reducing GSN expression and promoting actin cytoskeleton remodeling and tumor progression." (PMID 35941115, 2022). "As a transcription factor, HBP1 inhibits its target genes by directly binding to specific affinity elements, such as N-MYC, C-MYC, p47phox, DNMT1 and EZH2, all of which are oncogenes or genes that promote tumor development." (PMID 33794968, 2021). "Quantitative RT–PCR (RT-qPCR) analysis demonstrated a decrease or absence of HBP1 transcripts in 31.7% (26/82) of tumour tissues compared to their corresponding normal tissues." (PMID 24895061, 2014). "The data indicated that 30.5% (25/82) of tumours showed reduced or absent expression of HBP1 while β-catenin nuclear accumulation was found in 40.2% (33/82) of NSCLC, respectively." (PMID 24895061, 2014). "For example, DKK1, HTATIP2, HBP1, MXI1 and CASP7, all bound by RBM47 and upregulated upon RBM47 reintroduction, have known tumor suppressive functions." (PMID 24898756, 2014). "This corresponds to previous findings, where HBP1 has been seen to have a negative effect on tumours." (PMID 16001974, 2005). "In addition, HBP1 and SFRP1 included in the models are known to function as suppressors of cancer progression by suppressing β-catenin transactivation, and cell adhesion-related genes are involved in tumor invasion or metastasis." (PMID 29270240, 2017). "Additionally, a link between oncogenic Wnt/β-catenin signaling and HBP1 has been established by the finding that HBP1 physically interacts with two distinct domains in TCF4 to prevent its DNA binding and the resultant Wnt/β-catenin target gene expression in tumor cells." (PMID 23613959, 2013).
cancer (20 papers, 2014 to 2024). A tumor composed of atypical neoplastic, often pleomorphic cells that invade other tissues. "HBP1 is located in chromosome 7q31.1, a region that is found usually deleted in several cancer types and 30% of BCa patients have mutants or variants of HBP1." (PMID 34681793, 2021). "The identification of MDM2 overexpression leading to an inhibition of DNA break repair and causing cell death by repressing HBP1 also opens up new therapeutic avenues for cancer therapy." (PMID 30816344, 2019). "Taken together, alterations of the HBP1 transcriptional repressor were associated with the invasion and migration ability of cancer cells 45, 46, which was consistent with our experiments result." (PMID 29663730, 2018). "Additionally, high amounts of HBP1 methylation is associated with poor prognosis of cancer patients." (PMID 35941115, 2022). "The methylated HBP1-GSN axis is associated with the clinical outcomes of cancer patients." (PMID 35941115, 2022). "High-mobility group box-containing protein 1 (HBP1) is a transcription factor to function as a tumor suppressor in various cancers." (PMID 36677584, 2023). "Several micro-RNAs can epigenetically regulate the expression of HBP1 in cancer cells, such as miR-17-5p and miR-21, which can improve cell proliferation, invasion and migration by decreasing the expression of HBP1." (PMID 35941115, 2022). "MiR-17-5p has been shown in cellular assays to play an important role in cancer cell invasion and migration by suppressing HBP1 and consequently Wnt/β-catenin." (PMID 31581940, 2019). "We propose that the HBP1-dependent functions of MDM2 should be considered in the design of anti-cancer drugs." (PMID 30816344, 2019). "In the context of cancer, several lines of evidence underscore the importance of the HBP1 transcription factor." (PMID 27129219, 2016). "Among these genes, HBP1, released by oxidative stress-induced ROS, has been recently reported that its decreased expression in A549 cells significantly increased cancer cell migration and invasion in vitro, as well as liver metastasis in vivo." (PMID 26543233, 2015). "We therefore hypothesized that inhibiting HBP1 methylation could be used as a novel cancer treatment method." (PMID 35941115, 2022). "Hbp1 is a transcription factor and a potent cell cycle inhibitor in normal and cancer cells, it activates or represses the expression of different cell cycle genes through direct DNA binding, cofactor recruitment, chromatin remodeling, or neutralization of other transcription factors." (PMID 32245399, 2020). "As an oncoprotein, MDM2 could contribute DNA damage repair dysfunction and promote cell death by repressing HBP1, which makes it a potential target for cancer therapy." (PMID 30816344, 2019). "From the cancer standpoint, we predict that combining cell cycle arrest with DNA damage repair via the MDM2/HBP1 axis might have therapeutic potential for human cancer." (PMID 30816344, 2019). "HBP1 is an endogenous inhibitor of the Wnt signaling pathway in both normal and cancer cells." (PMID 30619295, 2018). "In addition, accumulated evidence also supports a role of FOXO1 and HBP1 in metastatic potential of cancer cells." (PMID 28099936, 2017). "The results from either array or RNA sequencing data supported the negative correlation between HBP1 and EZH2, whereas positive correlation between HBP1 and p21 also existed in cancers and suggested their potential roles in regulation of tumorigenesis for many cancer types." (PMID 27129219, 2016). "Targeting methylated HBP1-GSN axis may provide a therapeutic strategy for cancer." (PMID 35941115, 2022). "HBP1 pathway could also be modulated by other factors, therefore influencing cancer development." (PMID 29663730, 2018).
cancer (continued). "For HBP1, we would suggest that decreased HBP1 expression might contribute to interruption of senescence and the deregulation of some signaling pathways (Wnt, EGF receptor) that are linked to a poor prognosis in breast and other cancers." (PMID 27129219, 2016). "MMP13 knockdown significantly reduced invasion enhanced by HBP1 siRNA, suggesting a role of MMP13 in cancer invasion and metastasis." (PMID 36677584, 2023). "Meanwhile, we also chose 5 random cancer-related genes for mRNA detection, and found that GADD45A, HBP1, and SESN2 were significantly up-regulated, whereas KIF20A and TOP2A were down-regulated, compared to the 0 h group (*P < 0.05)." (PMID 32850392, 2020). "To strengthen a potential clinical significance, we screened and analyzed the differential expression of HBP1, EZH2, and p21 in some human cancers through the TumorProfile database." (PMID 27129219, 2016). "More studies are needed to investigate the possible prognostic and therapeutic potential of HBP1, p21, and EZH2 in cancers." (PMID 27129219, 2016). "Therefore, strategies to increase HBP1 expression may be useful for cancer prevention or treatment." (PMID 24895061, 2014). "Methylated HBP1 protein is less stable compared with non-methylated HBP1, which may explain why HBP1 protein levels are low in diverse cancer types." (PMID 35941115, 2022). "This completely different role for HBP1 in the development of malignant tumors demonstrated that the context of up-stream molecules of HBP1 in different cancers was not different, though this did lead to differences in the roles of HBP1 and the molecular mechanism." (PMID 29367693, 2018). "However, the role of HBP1 in relation to β-catenin nuclear accumulation has not been addressed in human cancer patients." (PMID 24895061, 2014).
infection (3 papers, 2011 to 2019). The state of being infected such as from the introduction of a foreign agent such as serum, vaccine, antigenic substance or organism. "Then we overexpressed HBP1 through lentiviral infection in MCF-7 and MDA-MB-231 cells." (PMID 30816344, 2019). "We then co-transfected MDM2, or both MDM2 and HBP1 into H1299 cells, and knocked down MDM2, or both MDM2 and HBP1 through lentiviral infection." (PMID 30816344, 2019). "The down-regulated miR-29b and miR-29a are both or each connected to up-regulated SMARCE1, HBO1, NKX6-1, HOXA10, HBP1, OTUD4, that could be further considered as potent targets during infection." (PMID 21408164, 2011).
HBP1 also shares sentences with these, for which no sentence is quoted: cervical tumor (2 papers); glioblastoma (2); oral squamous cell carcinoma (2); acute coronary syndrome (1); adenocarcinoma (1); astrocytoma (1); B cell lymphoma (1); brain cancer (1); chondrosarcoma (1); colorectal adenocarcinoma (1); eosinophilic leukemia (1); ependymoma (1); esophageal squamous cell carcinoma (1); Infertility (1); leukemia (1); liver cirrhosis (1); lung squamous cell carcinoma (1); non-small cell lung carcinoma (1); ovarian carcinoma (1); pancreatic cancer (1); pituitary adenomas (1); rectum cancer (1); rheumatoid arthritis (1); skin cancer (1); stomach cancer (1); Stroke (1); thyroid cancer (1); type 2 diabetes mellitus (1); uterine cancer (1).